PCNT (pericentrin)
Description:
Integral component of the filamentous matrix of the centrosome involved in the initial establishment of organized microtubule arrays in both mitosis and meiosis. Plays a role, together with DISC1, in the microtubule network formation. Is an integral component of the pericentriolar material (PCM). May play an important role in preventing premature centrosome splitting during interphase by inhibiting NEK2 kinase activity at the centrosome.
Synonyms: KIAA0402; PCNT2; KEN; PCN; PCNTB; SCKL4; MOPD2; PCTN2
Tractability: PROTAC: UniProt records ubiquitination sites on it; ubiquitination databases record sites on it; its protein half-life has been measured.
Gene: Protein-coding gene on chromosome 21 (46,324,124 to 46,445,769, forward strand). Ensembl gene ENSG00000160299.
Subcellular location: Cytoplasm, cytoskeleton, microtubule organizing center, centrosome
Subcellular location (Human Protein Atlas): Centrosome; Centriolar satellite; Cytosol; Flagellar centriole; Mid piece
Pathways (Reactome):
Cell Cycle: AURKA Activation by TPX2; Loss of Nlp from mitotic centrosomes; Loss of proteins required for interphase microtubule organization from the centrosome; Recruitment of NuMA to mitotic centrosomes; Recruitment of mitotic centrosome proteins and complexes; Regulation of PLK1 Activity at G2/M Transition
Autophagy: Aggrephagy; Chaperone Mediated Autophagy; Late endosomal microautophagy
Organelle biogenesis and maintenance: Anchoring of the basal body to the plasma membrane
Gene Ontology:
Molecular function: protein binding; molecular adaptor activity
Biological process: cilium assembly; microtubule cytoskeleton organization; mitotic spindle organization; positive regulation of intracellular protein transport; microtubule nucleation; signal transduction
Cellular component: centriolar satellite; centriole; centrosome; membrane; cytosol; cytoplasm; microtubule organizing center
Genetic constraint (gnomAD): Loss-of-function variants: 297 observed, 346.84 expected, observed/expected ratio (o/e) 0.86, 90% interval 0.78 to 0.94. The upper end of that interval is the gene's LOEUF score, 0.94, which puts it in group 4 of 6, group 1 being the genes least tolerant of losing a copy. Missense variants: 4,223 observed, 4,142.7 expected, observed/expected ratio (o/e) 1.02, 90% interval 0.99 to 1.05. Synonymous variants: 1,777 observed, 1,702.6 expected, observed/expected ratio (o/e) 1.04, 90% interval 1 to 1.09.
Gene-disease validity (ClinGen):
ClinGen rates the evidence that PCNT causes each of these diseases.
microcephalic osteodysplastic primordial dwarfism type II (autosomal recessive): Definitive. A form of microcephalic primordial dwarfism (MPD) characterized by severe pre- and postnatal growth retardation, with marked microcephaly in proportion to body size, skeletal dysplasia, abnormal dentition, insulin resistance, and increased risk for cerebrovascular disease.
Homologues: Orthologues: chimpanzee PCNT (96% identical), macaque PCNT (82% identical), rabbit PCNT (64% identical), dog PCNT (59% identical), guinea pig PCNT (56% identical), rat Pcnt (54% identical), mouse Pcnt (53% identical), tropical clawed frog pcnt (31% identical), zebrafish pcnt (29% identical). Paralogues in human: AKAP9 (22% identical).
Diseases named in the same sentence as PCNT in open-access papers:
PCNT is named in the same sentence as 79 diseases in open-access papers, as found by Europe PMC text mining. Sharing a sentence is not in itself a finding about the gene and the disease. The quoted sentences say what the papers report.
microcephalic osteodysplastic primordial dwarfism type II (17 papers, 2008 to 2026). "We report a novel frameshift variant in the PCNT gene and a previously unreported phenotype for Microcephalic Osteodysplastic Primordial Dwarfism (MOPD) Type II." (PMID 35422036, 2022). "Critical homozygous or compound heterozygous variants in PCNT are a known cause of microcephalic osteodysplastic primordial dwarfism type II accompanied by mandibular hypoplasia, which is similar to the maxillofacial phenotype in this patient." (PMID 31311520, 2019). "More than 30 described mutations in PCNT cause failure in centrosome division, resulting in microcephalic osteodysplastic primordial dwarfism type II (MOPDII), which is characterized by short bones and microcephaly." (PMID 29567674, 2018). "It is now believed that mutations in PCNT cause the phenotypically very similar disease Primary microcephaly and microcephalic osteodysplastic primordial dwarfism type II (MOPD II)." (PMID 26919047, 2016). "In fact, mutations in pericentrin are linked to a number of congenital disorders, including microcephalic osteodysplastic primordial dwarfism type II." (PMID 24466316, 2014). "Mutations in PCNT (pericentrin), another centrosomal protein, have been associated with both Seckel syndrome and the overlapping dwarfism disorder, microcephalic osteodysplastic primordial dwarfism type II (MOPDII)." (PMID 23166506, 2012). "MOPD type II is caused by mutations in PCNT encoding a key centrosomal protein." (PMID 28630177, 2017). "In this study, we investigate a rare variant of the centrosome-associated protein Pericentrin, which was discovered in a single family with Majewski/microcephalic osteodysplastic primordial dwarfism type II (MOPD II)." (PMID 42146478, 2026). "Variants of or loss of pericentrin (PCNT) have been implicated in microcephalic primordial dwarfism disorders, including Majewski osteodysplastic primordial dwarfism type II (MOPD II)." (PMID 40230260, 2025). "At 2 years of age, assessment by clinical geneticist led to a clinical suspicion of microcephalic osteodysplastic primordial dwarfism type II (MOPDII), an autosomal recessive condition caused by PCNT mutations." (PMID 33584815, 2020). "Recently, loss-of-function studies of human PCNT have established a causal link between PCNT mutations and the early onset of T2DM in microcephalic osteodysplastic primordial dwarfism type II (MOPD II) patients." (PMID 26083368, 2015).
Seckel syndrome (11 papers, 2008 to 2025). A rare autosomal recessive inherited syndrome caused by mutations in the ATR gene, RBBP8 gene, CENPJ gene, CEP152 gene, CEP63 gene, NIN gene, DNA2 gene, or TRAIP gene. "This includes mutations in the DNA damage response kinase ATR as a cause of Seckel syndrome and PCNT mutations, which have been identified in MOPDII." (PMID 24711643, 2014). "Mutations in pericentrin (PCNT2)/kendrin which encodes a structural centrosomal protein, were identified in several Seckel syndrome patients all of which exhibited defective ATR-pathway function." (PMID 19440510, 2008). "PCNT mutations cause MPD, specifically, MOPD2 or Seckel syndrome." (PMID 37443841, 2023). "In addition, recent studies found that mutations in PCNT cause Seckel syndrome, defects in ATR-dependent DNA damage signaling, which displays mitotic failure and cell death, revealing PCNT functions in the DDR." (PMID 35805981, 2022). "One of them actually claims that mutations in PCNT can cause Seckel Syndrome." (PMID 26919047, 2016). "In addition, MOPD II and Seckel syndrome, diseases strongly associated with moyamoya angiopathy, are sometimes caused by mutations in the pericentrin gene." (PMID 23518061, 2013). "In contrast to cells from ATR-, CtIP-, CEP152- and PCNT-Seckel syndrome patients, we have shown that MEFs from Cenpj-deficient mice are not impaired in ATR-dependent DNA damage signaling but instead show an elevated frequency of extra centrioles, multipolar spindles, and near tetraploid karyotypes." (PMID 23166506, 2012). "Likewise, the phenotype of Seckel syndrome caused by a novel CENPJ variant was aggravated to microcephalic osteodysplastic primordial dwarfism type II (MOPDII) in conjunction with an additional PCNT variant." (PMID 34068194, 2021). "Microcephalic osteodysplastic primordial dwarfism type II (MOPDII) (OMIM 210,720) is caused by pathogenic variants of PCNT (OMIM 605,925), which are also associated with other human disorders including Seckel syndrome." (PMID 34284742, 2021). "Here, we propose that heterozygous variants of WDR62, CEP63, RAD50 and PCNT contribute to additional neurological and extra-neurological abnormalities in affected siblings of the families manifesting MCPH or Seckel syndrome." (PMID 34068194, 2021).
primordial dwarfism (9 papers, 2009 to 2023). "Microcephalic osteodysplastic primordial dwarfism type II (MOPDII) is the most common form of primordial dwarfism, caused by bialleic mutations in the pericentrin gene (PCNT)." (PMID 34016138, 2021). "Microcephaly osteodysplastic primordial dwarfism disease pericentrin mutations impair the Cep57-pericentrin interaction and lead to PCM disorganization." (PMID 30804344, 2019). "Other genes associated with microcephalic primordial dwarfism shown to cause defects in centrosomal and spindle microtubule function include: PCNT, CENPE and POC1A." (PMID 28334956, 2017). "Mutations in human pericentrin have recently been reported to cause primordial dwarfism and associated clinical disorders including episodes of hyperinsulinemia and early onset of diabetes." (PMID 20676397, 2010). "In accordance with the findings in primordial dwarfism of Majewski type 2 caused by pericentrin (PCNT) mutation and in Werner syndrome caused by WRN mutation, severe insulin resistance is not congenital in these patients but appears during late childhood or adolescence." (PMID 36627765, 2023). "Mutations in the Pericentrine gene (PCNT) cause primordial dwarfism." (PMID 24928221, 2014).
breast carcinoma (7 papers, 2015 to 2022). "A clinically applicable method for scoring functionally relevant centrosome aberrations by IHC, based on the area of pericentrin stained foci, was recently developed and validated in breast cancer tissues and cell line FFPE sectional pellets." (PMID 35474453, 2022). "Our results demonstrate that ALG-2 overexpression in breast cancer cells disrupts the localization of γ-tubulin and pericentrin and results in the formation of centrosome protein aggregates." (PMID 27926525, 2017). "To this end, we mined publically-available microarray data of breast cancer patients to evaluate gene expression levels for major structural centrosomal proteins, both centriolar (centrin) and pericentriolar (pericentrin and γ-tubulin)." (PMID 25868856, 2015). "Similarly to breast cancer cell lines, centriole number correlates with all three measurements of pericentrin, with pericentrin area showing the best correlation." (PMID 32255253, 2020). "The effects of treatment with Sepin-1 that are similar on the four breast cancer cell lines include non-activation of caspases 3 and 7 and downregulation of cell cycle-driving proteins, such as Raf, FoxM1, Plk1, Cdk1, Aurora A, Lamin B1, and pericentrin." (PMID 29780443, 2018).
microcephaly (7 papers, 2009 to 2021). A congenital or acquired developmental disorder in which the circumference of the head is smaller than normal for the person's age and sex. "Compound heterozygous mutations in PCNT cause microcephalic osteodysplastic primordial dwarfism type II, which is characterized by intrauterine growth retardation, severe proportionate short stature, and microcephaly." (PMID 31566912, 2019). "Furthermore, there is evidence that CEP215 interaction with pericentrin is critical for the microcephaly phenotypes." (PMID 24466316, 2014).
Down syndrome (6 papers, 2022 to 2025). "Malfunction of PCNT gene causes premature aging, brain development, and inflammatory- and immune-related Down syndrome–related responses associated with PCNT mutations." (PMID 38724875, 2024). "Trisomy 21, the genetic cause of Down syndrome, disrupts primary cilia formation and function, in part through elevated Pericentrin, a centrosome protein encoded on chromosome 21." (PMID 36656118, 2023). "The overexpression of HSA21 genes like DYRK1A, PDE9A, PCP4, and PCNT in Down syndrome disrupts calcium homeostasis, primarily by suppressing the calcineurin pathway." (PMID 41274866, 2025). "Consistent with cultured trisomy 21 cells, a mouse model of Down syndrome with elevated Pericentrin has fewer primary cilia in cerebellar granule neuron progenitors and thinner external granular layers at P4." (PMID 36656118, 2023). "But it is unclear how Pericentrin disrupts cilia assembly, and how this may contribute to the medical conditions observed in individuals with Down syndrome." (PMID 36656118, 2023). "Our findings on the collaborative role of CEP97 and Dyrk1a in multiciliation may add to our existing knowledge regarding pericentrin overexpression in patients with trisomy 21 and therapeutic approaches for the respiratory diseases in patients with ciliopathy and Down syndrome." (PMID 34787650, 2022).
ciliopathies (5 papers, 2010 to 2024). "Inactivating mutations of pericentrin lead to cell cycle checkpoint and microtubule organization defects, resulting in mitotic arrest, dwarfism and ciliopathies, whereas pericentrin overexpression is seen in cancers and correlates with chromosomal instability." (PMID 20169156, 2010). "Interestingly, adipocyte dysfunction has also been shown in other monogenic ciliopathies, such as Alström and Bardet-Biedl syndromes, and lipodystrophic features are part of the primordial dwarfism syndrome due to pathogenic variants in PCNT, encoding the centrosomal protein pericentrin." (PMID 39017987, 2024).
Insulin resistance (5 papers, 2012 to 2023). Increased resistance towards insulin, that is, diminished effectiveness of insulin in reducing blood glucose levels. "The aim of this study was to investigate the regulating effect of pericentrin (PCNT) on insulin secretion in the development of insulin resistance and to determine the underlying mechanism." (PMID 26083368, 2015). "Moreover, PCNT mutations lead to severe insulin resistance, dyslipidemia and diabetes in the context of microcephalic osteodysplastic primordial dwarfism type 2 (MOPDII)." (PMID 30421101, 2019). "Defects in pericentrin are associated with severe insulin resistance and diabetes mellitus." (PMID 22693602, 2012). "Of note, mutations in genes encoding the centrosomal proteins pericentrin (PCNT) and POC1A are associated with severe insulin resistance, while disruption of the centrosomal protein CEP19 causes morbid obesity." (PMID 30421101, 2019). "In this study, PCNT was highly expressed in tissues and organs that are closely related with insulin resistance, such as subcutaneous fat, skeletal muscle, liver, and pancreas." (PMID 26083368, 2015).
dwarfism (4 papers, 2010 to 2021). "Intriguingly, mutations in the PCNT gene, which encodes pericentrin, are heavily implicated in a form of dwarfism associated with reduced brain size, suggesting it to be important for neurodevelopment." (PMID 21195721, 2012). "Recently, loss-of-function mutations in another centrosomal gene, human pericentrin, have been causally linked to a severe form of dwarfism and microcephaly." (PMID 20676397, 2010). "Although, in our patient the profound growth deficit certainly is caused by the aberrant pericentrin genes/proteins, such findings suggest that dwarfism-like phenotypes can also be provoked by IGF1R mutations under specific, adverse genetic or environmental conditions." (PMID 22693602, 2012). "Although the cell cycle defects resulting from pericentrin mutations provide a plausible mechanism for the dwarfism associated with MOPD II, the mechanism linking pericentrin with dysregulated glucose homeostasis and diabetes is unknown." (PMID 20676397, 2010).
schizophrenia (4 papers, 2011 to 2021). A major psychotic disorder characterized by abnormalities in the perception or expression of reality. "In addition Pericentrin 2 encoded by Pcnt2 found in the Ms4Yah deleted interval has been associated with schizophrenia and bipolar disorder by several studies and is known to interact with Disc-1." (PMID 21047530, 2011). "We applied the framework to seventeen phenotypes and found well-replicated genes such as HERC2 and OCA2 for hair and eye color, and novel genes such as ZNF773 and PCNT for schizophrenia." (PMID 34535759, 2021). "Disrupted in schizophrenia 1 (Disc1), pericentriolar material 1 (PCM-1), and human jouberin (Abelson helper integration site 1 (AHI1)) are linked with schizophrenia, hamartin (Tuberous sclerosis 1 (TSC1)) is linked with autism, and pericentrin (PCNT), DCDC2, and Dyx1c1 are linked with dyslexia." (PMID 28125008, 2017). "The genes ZNF773, PCNT, and DYSF were assigned the highest weights by the neural network and were thus considered to be the most predictive genes for schizophrenia." (PMID 34535759, 2021).
diabetes (3 papers, 2010 to 2022). "While the link between centrosomal and cell cycle defects may account for growth deficiencies, the mechanism linking pericentrin mutations with dysregulated glucose homeostasis and pre-pubertal onset of diabetes is unknown." (PMID 20676397, 2010).
Primary microcephaly (3 papers, 2016 to 2021). Head circumference below 2 standard deviations below the mean for age and gender at birth. "Rs13301996 is intronic to CDK5RAP2, which encodes a regulator of CDK5 activity, interacts with CDK5R1 and pericentrin (PCNT), plays a role in centriole engagement and microtubule nucleation and has been linked to primary microcephaly and Alzheimer’s disease." (PMID 34165540, 2021).
Breast tumor (2 papers, 2014 to 2016). "An average of 78 % of pericentrin foci contained this centriolar marker in normal samples compared to an average of 46 % in breast tumors." (PMID 26832928, 2016). "Breast tumor cells in control lungs with invasive metastases show a high level of centrosomal abnormalities by immunofluorescence staining for pericentrin." (PMID 25485753, 2014).
cerebrovascular disease (2 papers, 2020 to 2025). "Our data support a role of sequence variants in PCNT, RNF213 and THSD1 as susceptibility factors for cerebrovascular disease." (PMID 32367296, 2020). "In a cohort study of familial intracranial aneurysms, PCNT was found that it may be a highly credible candidate gene for cerebrovascular diseases." (PMID 40722175, 2025).
dyslexia (2 papers, 2010 to 2017). A learning disorder characterized by an impairment in processing written words. "PCNT might also be important for susceptibility to dyslexia, because PCNT is localized on the chromosome region 21q22.3, and a deletion in this region was associated with dyslexia in the case of a dyslectic father and his three sons." (PMID 28125008, 2017). "The recent identification of S100B as a novel dyslexia candidate gene along with three other genes (i.e., PCNT, DIP2A, and PRMT2) mapping to chromosome region 21q22.3 suggests that decreases in S100B expression might contribute to certain dyslexia phenotypes." (PMID 20827421, 2010).
microcephalic osteodysplastic primordial dwarfism (2 papers, 2010 to 2022). "Recently, mutations in the centrosomal protein, pericentrin, have been linked to human microcephalic osteodysplastic primordial dwarfism (MOPD II), a rare genetic disease characterized by severe growth retardation and early onset of type 2 diabetes among other clinical manifestations." (PMID 20676397, 2010).
moyamoya angiopathy (2 papers, 2013 to 2019). "The other female subject had moyamoya disease, but a genetic study revealed a normal PCNT gene." (PMID 31510961, 2019).
trisomy 21 (2 papers, 2022 to 2023). A chromosomal disorder consisting of the presence of an extra chromosome 21. "We previously showed that elevated PCNT protein is sufficient for decreased ciliation in trisomy 21 cells." (PMID 36656118, 2023).
ZIKV infection (2 papers, 2022 to 2023). "The functions of several mitosis-associated proteins, CEP152 and pericentrin (centrosomal), CENPJ (centromere) and TBK1 kinase (centrosomal) are affected during ZIKV infection, leading to mitotic defects and premature differentiation or cell death." (PMID 35412344, 2022).